UBTD1 (ubiquitin domain containing 1)
Synonyms: FLJ11807
Tractability: Antibody: the Human Protein Atlas places it where antibodies can reach. PROTAC: ubiquitination databases record sites on it.
Gene: Protein-coding gene on chromosome 10 (97,498,913 to 97,571,206, forward strand). Ensembl gene ENSG00000165886.
Subcellular location (Human Protein Atlas): Vesicles; Cytosol; Plasma membrane
Gene Ontology:
Molecular function: protein binding
Genetic constraint (gnomAD): Loss-of-function variants: 19 observed, 21.72 expected, observed/expected ratio (o/e) 0.87, 90% interval 0.61 to 1.28. The upper end of that interval is the gene's LOEUF score, 1.28, which puts it in group 5 of 6, group 1 being the genes least tolerant of losing a copy. Missense variants: 282 observed, 317.54 expected, observed/expected ratio (o/e) 0.89, 90% interval 0.81 to 0.98. Synonymous variants: 116 observed, 136.43 expected, observed/expected ratio (o/e) 0.85, 90% interval 0.73 to 0.99.
Homologues: Orthologues: chimpanzee UBTD1 (100% identical), macaque UBTD1 (100% identical), dog UBTD1 (99% identical), rat Ubtd1 (99% identical), guinea pig UBTD1 (99% identical), mouse Ubtd1 (99% identical), pig UBTD1 (98% identical), rabbit UBTD1 (97% identical), tropical clawed frog ubtd1 (78% identical), zebrafish ubtd1b (72% identical), zebrafish ubtd1a (65% identical), Drosophila melanogaster CG1172 (51% identical). Paralogues in human: UBTD2 (65% identical).
Diseases named in the same sentence as UBTD1 in open-access papers:
UBTD1 is named in the same sentence as 13 diseases in open-access papers, as found by Europe PMC text mining. Sharing a sentence is not in itself a finding about the gene and the disease. The quoted sentences say what the papers report.
hepatocellular carcinoma (4 papers, 2020 to 2024). A malignant tumor that arises from hepatocytes. "In lung, prostate, and hepatocellular cancer, researchers found that UBTD1 is found to catalyze Yes1-associated transcriptional regulator (YAP) protein degradation and inhibit the development of lung, prostate, and hepatocellular cancer." (PMID 39003255, 2024). "Other mechanosensors promoting EMT via several pathways such as transient receptor potential melastatin 7 (TRPM7)/SOX4 in breast cancer, CXCR4/ubiquitin domain containing 1 (UBTD1)/YAP in hepatoma and EGFR in glioblastoma have been reported." (PMID 36906534, 2023).
colorectal cancer (2 papers, 2024 to 2025). A primary or metastatic malignant neoplasm that affects the colon or rectum. "In order to understand the potential biological function of UBTD1 in colorectal cancer, we first examined the expression of UBTD1 in CRC samples and adjacent normal tissues, and its association with patients’ survival." (PMID 39003255, 2024). "Compared to adjacent normal tissues, the expression of UBTD1 mRNA in colorectal cancer was significantly higher in 38 pairs of colorectal cancer and corresponding adjacent normal tissues from FUSCC (P < 0.001)." (PMID 39003255, 2024).
lymph node metastasis (1 paper, 2024). "Higher UBTD1 expression was significantly associated with poorer survival and more lymph node metastasis." (PMID 39003255, 2024). "We explored the association between UBTD1 expression and clinicopathological characteristics of CRC patients using data from TCGA, and found that UBTD1 expression was associated with lymph node metastasis and TNM stage, but not significantly correlated with age, gender and cancer types." (PMID 39003255, 2024).
prostate carcinoma (1 paper, 2024). A carcinoma that arises from epithelial cells of the prostate gland. "An additional study reported that UBTD1 can interact with another E3 ligase, RNF26, to upregulate the ubiquitination of autophagy-related protein p62 and enhance the lysosomal degradation of EGFR in prostate cancer cells." (PMID 39003255, 2024).
cancer (6 papers, 2020 to 2024). A tumor composed of atypical neoplastic, often pleomorphic cells that invade other tissues. "Importantly, a decreased expression of UBTD1 is associated with increased cancer aggressiveness and decreased overall patient survival in colorectal, liver, prostate, and lung cancer." (PMID 33884955, 2021). "UBTD1 has been reported to play significant roles in various cancers, with its downstream mechanisms varying accordingly." (PMID 39003255, 2024). "The ubiquitin-like protein UBTD1 plays a pivotal role in the degradation of key proteins in various cancer cells by interacting with E3 ligases, significantly influencing cancer progression and invasion." (PMID 39003255, 2024). "In our study, we analyzed CRC patients’ clinical information and UBTD1 expression data, and found that the expression of UBTD1 in cancer tissue was significantly higher than that in adjacent normal tissue." (PMID 39003255, 2024). "Consistent with the findings in our own dataset, the expression of UBTD1 was higher in CRC tissues than that in adjacent normal tissues from The Cancer Genome Atlas (TCGA) dataset both in paired samples and in grouped samples." (PMID 39003255, 2024). "It was found that UBTD1 was upregulated in cancer tissues in most cases (four cases/five cases)." (PMID 39003255, 2024). "This last finding underlines the importance of UBTD1 in EGFR-driven cell proliferation and may be further investigated in an EGFR hyper-activated state such as cancer." (PMID 33884955, 2021). "Ubiquitin domain containing 1 (UBTD1), a ubiquitin-like protein, regulates UPS-mediated protein degradation and tumor progression in some cancer types." (PMID 39003255, 2024). "Previous studies found that UBTD1 can interact with E3 ligase β-TrCP to regulate the ubiquitination of oncoprotein YAP, leading to the degradation of YAP and suppression of cancer cells’ malignant phenotype." (PMID 39003255, 2024). "The stiff matrix promotes the expression of C-X-C motif chemokine receptor 4 (CXCR4) and decreases the level of ubiquitin domain-containing protein 1 (UBTD1), which is involved in the proteasome-dependent degradation of YAP, and finally enhances YAP activity in cancer cells." (PMID 35205794, 2022).
tumor (4 papers, 2020 to 2025). "Tumor growth curves revealed that UBTD1 overexpression significantly inhibited the tumor growth of HCC cells in mice (P < 0.05)." (PMID 32483419, 2020). "This interaction may provide insight into the dual role of UBTD1, which has been characterized as a tumor suppressor in some studies but behaves as an oncoprotein in CRC cells." (PMID 39003255, 2024). "Collectively, our study, as detailed below demonstrated that UBTD1 might act as a tumor promoter by upregulating glycolysis via β-TrCP/c-Myc/HK2 pathway in CRC." (PMID 39003255, 2024). "Additionally, in vivo studies have successfully demonstrated that the knockdown of c-Myc expression effectively reverses the augmented xenograft tumor proliferation facilitated by overexpression of UBTD1." (PMID 39003255, 2024). "We also established a subcutaneous tumor model to measure the effect of UBTD1 on HCC in vivo." (PMID 32483419, 2020). "UBTD1 expression was highly correlated with poor pathological features, including the TNM stage, venous invasion, tumor size, and overall survival." (PMID 32483419, 2020).
UBTD1 also shares sentences with these, for which no sentence is quoted: breast carcinoma (1 paper); diabetes (1); gastric cancer (1); glioblastoma (1); Insulin resistance (1); lung carcinoma (1); Type 2 Diabetes (1).